EGLN3 (egl-9 family hypoxia inducible factor 3)
Description:
Prolyl hydroxylase that mediates hydroxylation of proline residues in target proteins, such as PKM, TELO2, ATF4, GPX4 and HIF1A. Target proteins are preferentially recognized via a LXXLAP motif. Cellular oxygen sensor that catalyzes, under normoxic conditions, the post-translational formation of 4-hydroxyproline in hypoxia-inducible factor (HIF) alpha proteins. Hydroxylates a specific proline found in each of the oxygen-dependent degradation (ODD) domains (N-terminal, NODD, and C-terminal, CODD) of HIF1A. Also hydroxylates HIF2A. Has a preference for the CODD site for both HIF1A and HIF2A. Hydroxylation on the NODD site by EGLN3 appears to require prior hydroxylation on the CODD site. Hydroxylated HIFs are then targeted for proteasomal degradation via the von Hippel-Lindau ubiquitination complex. Under hypoxic conditions, the hydroxylation reaction is attenuated allowing HIFs to escape degradation resulting in their translocation to the nucleus, heterodimerization with HIF1B, and increased expression of hypoxy-inducible genes. Acts as an inhibitor of ferroptosis by mediating hydroxylation of GPX4, thereby preventing GPX4 degradation via chaperone-mediated autophagy. GPX4 hydroxylation is promoted by PSAT1, which provides 2-oxoglutarate substrate to EGLN3. ELGN3 is the most important isozyme in limiting physiological activation of HIFs (particularly HIF2A) in hypoxia. Also hydroxylates PKM in hypoxia, limiting glycolysis. Under normoxia, hydroxylates and regulates the stability of ADRB2. Regulator of cardiomyocyte and neuronal apoptosis. In cardiomyocytes, inhibits the anti-apoptotic effect of BCL2 by disrupting the BAX-BCL2 complex. In neurons, has a NGF-induced proapoptotic effect, probably through regulating CASP3 activity. Also essential for hypoxic regulation of neutrophilic inflammation. Also mediates hydroxylation of ATF4, leading to decreased protein stability of ATF4 (Probable).
Synonyms: PHD3; HIFPH3; HIFP4H3
Tractability: Small molecule: an approved drug acts on it; a high-quality ligand is known; it belongs to a druggable protein family. PROTAC: UniProt records ubiquitination sites on it; ubiquitination databases record sites on it; a small molecule that binds it is known.
Target class: Enzyme; Oxidoreductase
Gene: Protein-coding gene on chromosome 14 (33,924,227 to 34,462,774, reverse strand). Ensembl gene ENSG00000129521.
Subcellular location: Nucleus; Cytoplasm
Subcellular location (Human Protein Atlas): Cytosol
Pathways (Reactome):
Cellular responses to stimuli: Oxygen-dependent proline hydroxylation of Hypoxia-inducible Factor Alpha
Gene Ontology:
Molecular function: 2-oxoglutarate-dependent dioxygenase activity; hypoxia-inducible factor-proline dioxygenase activity; peptidyl-proline 4-dioxygenase activity; protein binding; ferrous iron binding; iron ion binding; L-ascorbic acid binding; oxidoreductase activity, acting on paired donors, with incorporation or reduction of molecular oxygen
Biological process: negative regulation of ferroptosis; protein hydroxylation; protein stabilization; cellular response to hypoxia; regulation of neuron apoptotic process
Cellular component: cytoplasm; cytosol; nucleus; nucleoplasm
Genetic constraint (gnomAD): Loss-of-function variants: 12 observed, 24.31 expected, observed/expected ratio (o/e) 0.49, 90% interval 0.31 to 0.8. The upper end of that interval is the gene's LOEUF score, 0.8, which puts it in group 3 of 6, group 1 being the genes least tolerant of losing a copy. Missense variants: 224 observed, 313.3 expected, observed/expected ratio (o/e) 0.71, 90% interval 0.64 to 0.8. Synonymous variants: 144 observed, 133.88 expected, observed/expected ratio (o/e) 1.08, 90% interval 0.94 to 1.24.
Homologues: Orthologues: chimpanzee EGLN3 (100% identical), macaque EGLN3 (99% identical), dog EGLN3 (99% identical), pig EGLN3 (99% identical), guinea pig EGLN3 (97% identical), rat Egln3 (97% identical), mouse Egln3 (97% identical), tropical clawed frog egln3 (72% identical), zebrafish egln3 (62% identical). Paralogues in human: EGLN1 (61% identical), EGLN2 (56% identical).
Diseases named in the same sentence as EGLN3 in open-access papers:
EGLN3 is named in the same sentence as 123 diseases in open-access papers, as found by Europe PMC text mining. Sharing a sentence is not in itself a finding about the gene and the disease. The quoted sentences say what the papers report.
breast carcinoma (23 papers, 2009 to 2025). "For instance, in breast cancer, diminished EGLN3 expression correlates with larger, less-differentiated tumors, while in pancreatic cancer, EGLN3 overexpression is associated with well-differentiated tumor occurrence." (PMID 38928200, 2024). "EGLN3 was documented to inhibit cells proliferation and metastasis in other tumors including prostate cancer, glioma, pancreatic cancer and breast cancer." (PMID 34112167, 2021). "Knockdown of other upregulated ABC genes including PRR13, EGLN3, HSD11B2, and MATN3 also inhibited the proliferation of various breast cancer cell lines (data not shown)." (PMID 32539762, 2020).
glioma (16 papers, 2011 to 2025). A benign or malignant brain and spinal cord tumor that arises from glial cells (astrocytes, oligodendrocytes, ependymal cells). "Similarly, for Rt-glioma cells infected with a Dox-inducible Egln3 construct, the presence of 1μg/mL Dox (6hrs) up-regulated the expression of Egln3 protein and caused ≈50% decreases in Hif-2α protein levels after a 6hr exposure to hypoxic conditions without significantly altering Hif-1α expression." (PMID 22905089, 2012). "Intermediate reductions in the expression of these genes were achieved in Rt-glioma Egln3 -Dox tumors due to a basal level of Egln3 expression by our construct (data not shown)." (PMID 22905089, 2012). "Consistent with our in vitro experiments, a quantitative analysis of total tumor transcript levels indicated that Dox-induced Egln3 reduced Vegf by ≈80%, Klf5 by ≈90% and Oct4 by ≈90% in Rt-gliomas." (PMID 22905089, 2012). "Clearly Egln3 participates as a regulator of many fundamental cellular processes, highlighting the complex nature of Egln3 function in glioma formation." (PMID 22905089, 2012). "Collectively, these data confirm a key role for Egln3 in glioma progression through the hydroxylation of Hifs and through the participation of Egln3 in non-hydroxylase-dependent signaling pathways (see Discussion)." (PMID 22905089, 2012). "In this study, we report for the first time the effects of Egln3 expression upon glioma progression in vivo." (PMID 22905089, 2012). "This analysis was necessary to determine a working concentration of Dox to evaluate the functional significance of Egln3 within glioma cells." (PMID 22905089, 2012). "The dosage and timing of Egln3 induction as well as the targeted expression of Egln3 to specific glioma cell types likely will prove to be important considerations in directing the tumor suppressing potential of Egln3." (PMID 22905089, 2012). "When glioma-forming cells were engrafted intracranially and induced to express Egln3, tumor aggressiveness decreased as evidenced by markedly increased survival of injected mice." (PMID 22905089, 2012). "Intriguingly, the hydroxylase-deficient Egln3H196A, exhibited tumor growth intermediate to mock-treated and Egln3-expressing human gliomas." (PMID 22905089, 2012). "Hu-glioma cells exhibited a dosage-dependent induction of Egln3 with doxycycline (Dox) levels of 0–1μg/mL." (PMID 22905089, 2012). "Within cultured glioma cells it has been suggested that Egln3 can support cell viability, by attenuating exaggerated Hif signaling." (PMID 22905089, 2012). "We conclude that Egln3 is a critical determinant of glioma formation and tumor vascular functionality." (PMID 22905089, 2012). "To assess this possibility, we inducibly-expressed Egln3 and assayed for effects in the Hif expression pattern of glioma cells." (PMID 22905089, 2012). "An analysis of the tumor vasculature revealed that elevated Egln3 normalized glioma capillary architecture, consistent with a role for Egln3 in eliciting decreases in the production of Hif-regulated, angiogenic factors." (PMID 22905089, 2012). "On the other hand, Egln3 protein was undetectable in Rt-glioma cells (normoxia and hypoxia) whereas Egln3 in Rt-NSCs exhibited a dramatic increase upon hypoxia induction." (PMID 22905089, 2012). "Based upon a critical role for Hifs in promoting tumor progression, it was reasonable to speculate that the induction of Egln3 might attenuate glioma growth." (PMID 22905089, 2012). "We next ascertained whether Egln3H196A affected the kinetics of tumor progression by injecting Hu-glioma cells expressing Egln3 or Egln3H196A under the control of a Dox-inducible promoter into the flanks of NSG mice." (PMID 22905089, 2012). "Low levels of Egln3 induction (0.25μg/mL Dox) reduced the transcription of Klf5 and the Hif-2α transcriptional target, Oct4 by ≈50% and ≈70%, respectively within Hu-glioma cells relative to hypoxia-treated controls." (PMID 22905089, 2012).
glioma (continued). "Here, we tested the hypothesis that Egl 9 homolog 3 (Egln3), a prolyl-hydroxylase that promotes Hif degradation, suppresses tumor progression of human and rodent glioma models." (PMID 22905089, 2012). "Since Egln3 was sufficient to induce decreases in Hif signaling in vitro, the expression of Egln3 might also influence blood vessel formation within glioma." (PMID 22905089, 2012). "To determine if Egln3 could influence the kinetics of glioma development in vivo, we stereotaxically-engrafted Hu-glioma cells expressing Egln3 under the control of a Dox-inducible promoter into the cerebral cortex of immuno-compromised (NSG) mice." (PMID 22905089, 2012). "Therefore, the introduction of Egln3 into Hu- and Rt-glioma cells was biased to uncouple the hypoxia-initiated adaptive responses mediated by Hif-2α relative to Hif-1α." (PMID 22905089, 2012). "Therefore, induction of Egln3 two weeks following engraftment significantly reduced overall Hu-glioma aggressiveness." (PMID 22905089, 2012). "Therefore, while the overall effect of Egln3 was to suppress Hu-glioma growth, our findings also raise the prospect of additional Egln3 effectors within glioma." (PMID 22905089, 2012). "According to this hypothesis, our observed decreases in tumor aggression upon Egln3 induction would be consistent with depressed levels of angiogenesis within Egln3-expressing Hu-gliomas." (PMID 22905089, 2012). "Our data suggest that Egln3 follows this precedent within glioma as well." (PMID 22905089, 2012). "This raised the possibility that the down-regulation of Egln3 might contribute to the progression and aggressiveness of some gliomas by accentuating the activity of Hif-mediated signaling within glioma cells." (PMID 22905089, 2012). "In this study, we have assessed the effects of Egln3 upon the development of glioma in vivo." (PMID 22905089, 2012). "Out of these NRGs, 19 NRGs (EGLN3, HILPDA, HMBS, HYOU1, BNIP3, etc.)were found to be enriched in glioma tissues while 13 genes (SLC4A1, IL6, EPAS1, ACE, HMOX1, etc.)were decreased compared to normal tissues." (PMID 37934582, 2023). "EGLN3 elaborates the growth-suppressive function by suppression of EGFR signaling, which independent to HIF1α and NF-κB in gliomas." (PMID 34112167, 2021). "We hypothesize that induction of Egln3 during the initial stages of tumor formation impaired cellular factors that are proposed to support tumor initiation such as Hif-2α and Oct4 and that later stage glioma progression was abrogated through reduced angiogenic signaling within the tumor." (PMID 22905089, 2012). "In contrast with mock-treated Hu-glioma cells that always initiated tumor formation, a single animal injected with Hu-glioma Egln3 +Dox failed to develop neurological symptoms after a ≈18 week period." (PMID 22905089, 2012). "Consistent with previous studies, Egln3H196A was expressed at levels comparable to wild-type Egln3 in Hu-glioma cells in vitro and did not promote the degradation of Hif-1α or Hif-2α." (PMID 22905089, 2012). "Microscopic analysis of the engraftment site of this Hu-glioma Egln3 +Dox animal confirmed that tumor formation had failed to occur." (PMID 22905089, 2012). "RT-QPCR and Western (Fure 2B) confirmed the absence of Egln3 expression in Hu-glioma cells and a hypoxia-dependent increase in Ms-NSCs." (PMID 22905089, 2012). "Since the relative absence of Egln3 correlated with Hif-2α expression in glioma cells, we predicted that the expression of Egln3 might be sufficient to influence the hypoxic response of these cells." (PMID 22905089, 2012).
gastric cancer (12 papers, 2013 to 2025). A primary or metastatic malignant neoplasm involving the stomach. "Similarly, gastric cancer exhibits a decrease in the mRNA level of EGLN3 in cancerous tissues compared to adjacent normal tissues." (PMID 38928200, 2024).
pancreatic cancer (11 papers, 2010 to 2024). "EGLN3 also plays important roles in human endothelial cells and cancers, including pancreatic cancer and glioblastoma." (PMID 31827636, 2019). "For example, overexpression of EGLN3 through the transforming growth factor beta 1 (TGF ß1) pathway has been found to be linked to cancer cell invasion, metastasis, and poor prognosis in pancreatic cancer." (PMID 39682235, 2024). "In addition, this study demonstrated the role of abnormal pathways such as Wnt and Notch in pancreatic cancer and identified new genes such as EGLN3, MMP9, and FOS KLF5 and other transcription factors involved in carcinogenesis." (PMID 36052088, 2022). "Notably, in pancreatic cancer, decreased expression of EGLN2 and EGLN3 resulted in the induction of angiogenic factors by HIF1A and TGF-β1 pathway and poor patient OS." (PMID 38928200, 2024).
glioblastoma (10 papers, 2011 to 2025). The most malignant astrocytic tumor (WHO grade IV). "In addition, this group observed increased hypermethylation of the promoter for the gene (EGLN3) for PHD3 in glioblastoma tumors compared to normal brain." (PMID 33799686, 2021).
renal cell carcinoma (9 papers, 2011 to 2025). "For instance, circ-AKT3 regulates miR-296-3p/E-cadherin signaling in diabetic nephropathy, while circ-EGLN3 influences miR-1299/IRF7 in renal cell carcinoma (RCC)." (PMID 41194001, 2025).
colorectal cancer (8 papers, 2012 to 2024). A primary or metastatic malignant neoplasm that affects the colon or rectum. "However, DNA methylation in the CpG island of the EGLN3 promoter region caused reduced expression of this gene in colorectal cancer and, similarly, in leukemic cell lines with decreased mRNA and protein expression." (PMID 38928200, 2024). "The effect of DPA on EGLN3 expression was validated in SW480 colorectal cancer cells, revealing a concentration-dependent upregulation in response to DPA." (PMID 38613073, 2024).
renal carcinoma (8 papers, 2011 to 2025). A carcinoma arising from the epithelium of the renal parenchyma or the renal pelvis. "Decreased EGLN3 expression was detected in prostate, breast, melanoma, and renal carcinoma cell lines." (PMID 38928200, 2024). "Untargeted metabolomics analysis in 786-O kidney carcinoma cells revealed an impact of EGLN3 depletion on the abundance of different cellular nucleotide components and nucleotide-related structures, such as cytosine and deoxycytidine." (PMID 32228647, 2020). "Furthermore, the EGLN3 promoter region was found to be hypermethylated in prostate, breast, melanoma, and renal carcinoma cell lines." (PMID 38928200, 2024).
clear cell renal cell carcinoma (7 papers, 2011 to 2024). "For example, in clear cell renal carcinoma, where HIF induction has a pathogenic role, EGLN3 is overexpressed." (PMID 38958823, 2024). "SNPs of EGLN3, a regulator of transcription factor HIF that affects apoptosis in hemangioblastoma and clear cell renal cancer, were associated with IGR and LDL-c." (PMID 23628382, 2013).
lung carcinoma (7 papers, 2012 to 2024). "Utilizing the GEPIA database, we revealed that only EGLN3 was upregulated in lung cancer tissues compared to normal tissues." (PMID 37842058, 2023). "Although the significance of EGLN3 within cancer cells including lung cancer cells has been extensively explored, the significance of EGLN3 hydroxylase activity in malignant and stromal cells remains poorly defined thus far." (PMID 35124697, 2022). "We showed that inactivation of EGLN3 in host cells retarded LLC lung cancer growth through programming the TME." (PMID 35124697, 2022). "Strikingly, our data highlight that EGLN3 hydroxylates and stabilizes Erk3, an attractive molecule orchestrating the initiation and progression and emerging as a therapy target of lung carcinoma." (PMID 35124697, 2022). "EGLN3 is critically important for growth of various cancers including lung cancer." (PMID 35124697, 2022). "Importantly, LLC lung cancer cells carrying inactive EGLN3 displayed a reduction of tumor burden via ameliorating immunosuppressive milieu and inducing LLC cell senescence." (PMID 35124697, 2022). "Manipulating EGLN3 activity holds promise for the treatment of lung carcinoma." (PMID 35124697, 2022). "Thus, our finding has been validated by other studies where the EGLN3 was reported to be vital for the growth of numerous cancers, including lung cancer." (PMID 36552262, 2022).
prostate carcinoma (7 papers, 2011 to 2025). A carcinoma that arises from epithelial cells of the prostate gland. "MicroRNA-1205 (miR-1205) promoted cell proliferation and increased the resistance to H2O2 induced apoptosis in castration resistant prostate cancer cell lines through its post-transcriptional regulation of the EGLN3 gene." (PMID 33799686, 2021). "EGLN3 was also documented as a proapoptotic factor in considerable work, including neural crest derivatives, osteosarcoma cells, prostatic carcinoma cells, lung carcinoma cells, and colorectal carcinoma cells." (PMID 34112167, 2021). "In contrast, by targeting EGLN3 and APC2, miR-1205 has an oncogenic role in castration-resistant prostate cancer and lung adenocarcinoma, respectively." (PMID 31801947, 2019).
diabetes (6 papers, 2016 to 2025). "EGLN3 is a hypoxic sensor and plays an important role in cancer and diabetes." (PMID 38755642, 2024).
pheochromocytoma (6 papers, 2008 to 2017). "Inactivating germline mutations in EGLN1 have been identified to cause erythrocytosis and deregulation of EGLN3 has been linked to the development of pheochromocytoma, a neuroendocrine tumor of the adrenal glands." (PMID 18773095, 2008). "However, it is possible that in individuals with type 1 VHL mutations, higher levels of HIF-2α and of the proapoptotic HIF target gene, EglN3, cause some culling of renal cells upon loss of the wild type allele, in a manner similar to as has been suggested for pheochromocytoma." (PMID 19602254, 2009). "Pheochromocytoma, a neuroendocrine tumor of the medulla of the adrenal glands, is linked with deregulation of PHD3/EGLN3." (PMID 18773095, 2008). "In addition, KIF1B has been reported to have a haploinsufficient tumor-suppressor function in primary neuroblastomas and pheochromocytomas by acting downstream from EglN3 prolyl hydroxylase." (PMID 23028799, 2012).
breast tumor (5 papers, 2009 to 2021). "Moreover, a simultaneous increase in the expression of CA9 and EGLN3 was observed in the study for the functional relationship between gene transcriptional activity and the response to lactic acidosis and hypoxia in breast tumor cells." (PMID 34046336, 2021).